MEGF11 (multiple EGF like domains 11)
Description:
May regulate the mosaic spacing of specific neuron subtypes in the retina through homotypic retinal neuron repulsion. Mosaics provide a mechanism to distribute each cell type evenly across the retina, ensuring that all parts of the visual field have access to a full set of processing elements (By similarity).
Synonyms: KIAA1781; DKFZp434L121
Tractability: Antibody: UniProt places it where antibodies can reach, with high confidence; UniProt predicts a signal peptide or a membrane-spanning region; its Gene Ontology location is reachable by antibodies, with medium confidence.
Gene: Protein-coding gene on chromosome 15 (65,895,079 to 66,253,811, reverse strand). Ensembl gene ENSG00000157890.
Subcellular location: Cell membrane; Basolateral cell membrane
Gene Ontology:
Molecular function: protein binding; extracellular matrix structural constituent
Biological process: homotypic cell-cell adhesion; retina layer formation; substrate adhesion-dependent cell spreading
Cellular component: basement membrane; basolateral plasma membrane; plasma membrane
Genetic constraint (gnomAD): Loss-of-function variants: 119 observed, 118.93 expected, observed/expected ratio (o/e) 1, 90% interval 0.86 to 1.16. The upper end of that interval is the gene's LOEUF score, 1.16, which puts it in group 5 of 6, group 1 being the genes least tolerant of losing a copy. Missense variants: 1,474 observed, 1,370.4 expected, observed/expected ratio (o/e) 1.08, 90% interval 1.03 to 1.12. Synonymous variants: 520 observed, 524.43 expected, observed/expected ratio (o/e) 0.99, 90% interval 0.92 to 1.07.
Homologues: Orthologues: chimpanzee MEGF11 (99% identical), pig MEGF11 (95% identical), rabbit MEGF11 (94% identical), rat Megf11 (90% identical), macaque MEGF11 (90% identical), guinea pig MEGF11 (89% identical), mouse Megf11 (86% identical), tropical clawed frog megf11 (66% identical), zebrafish megf11 (64% identical). Paralogues in human: MEGF10 (61% identical), MEGF6 (33% identical), GAS6 (11% identical).
Diseases named in the same sentence as MEGF11 in open-access papers:
MEGF11 is named in the same sentence as 9 diseases in open-access papers, as found by Europe PMC text mining. Sharing a sentence is not in itself a finding about the gene and the disease. The quoted sentences say what the papers report.
mastitis (3 papers, 2020 to 2023). Inflammation of breast tissue during lactation or postpartum due to an obstructed duct or infection. "SLC24A1 has also been shown to be downregulated in cows with subclinical mastitis, while MEGF11 is associated with somatic cell count in cattle." (PMID 35659541, 2022). "The MEGF11 gene regulates diurnal gain and immune response to mastitis in cattle." (PMID 37595009, 2023). "Moreover, rs43616983 is positioned within the MEGF11 gene, which regulated daily gain and immune response to mastitis in cattle." (PMID 33176675, 2020).
triple-negative breast carcinoma (3 papers, 2020 to 2023). An invasive breast carcinoma which is negative for expression of estrogen receptor (ER), progesterone receptor (PR), and human epidermal growth factor receptor 2 (HER2). "The recently published data confirm the association of IL-17 with the MEGF11 gene (multiple epidermal growth factor like domains 11), whose expression is significantly higher in the tumor tissue of triple-negative breast cancer patients who experienced relapse." (PMID 37427128, 2023). "Our previous study demonstrated that upregulation of multiple epidermal growth factor-like domains 11 (MEGF11) gene expression is involved in the mechanism by which recurrence of Triple Negative Breast Cancer (TNBC) occurs." (PMID 32415115, 2020).
breast carcinoma (1 paper, 2020). "In this study, we are the first to demonstrate that MEGF11 has a role in the mechanisms associated with breast cancer recurrence." (PMID 32415115, 2020). "Until the present study, there has been no information available on the role of MEGF11 in breast cancer." (PMID 32415115, 2020).
Hodgkins lymphoma (1 paper, 2023). A heterogeneous group of malignant lymphoid neoplasms of B-cell origin characterized histologically by the presence of Hodgkin and Reed-Sternberg (HRS) cells in the vast majority of cases. "It plays a critical role in white blood cells as a single nucleotide polymorphism (SNP) in the MEGF11 gene, which is strongly associated with the development of Hodgkin lymphoma." (PMID 38067609, 2023).
Obesity (1 paper, 2024). Accumulation of substantial excess body fat. "The candidate genes MIF, MAP2K3, HACD3, and MEGF11 excavated in this study are related to obesity and fat deposition." (PMID 39330807, 2024).
schizophrenia (1 paper, 2020). A major psychotic disorder characterized by abnormalities in the perception or expression of reality. "Blood brain barrier, brain damage, edema, and headache pathway effects, as well as a potential schizophrenia nodes with connections to MEGF10 and MEGF11 which binds Atrophin 1 (ATN1) a seizure related protein also appear." (PMID 32823271, 2020).
tumor (3 papers, 2020 to 2023). "They conclude that MEGF11 plays an important role in tumor survival and that overexpression of MEGF11 induces both a cytokine and a chemokine cascade, which will favor the tumor microenvironment in terms of distant metastasis." (PMID 37595009, 2023). "Our results demonstrate that MEGF11 play important role in tumour survival and that overexpression of MEGF11 induces both cytokine and chemokine cascades, which in turn will bring about modulation of the tumour microenvironments within TNBC cells." (PMID 32415115, 2020). "The present study shows that over-expressed MEGF11 upregulates the gene expression of BDNF/TrkB in TNBC cells, which suggests that MEGF11 plays a role in tumour cell-endothelial cell interactions." (PMID 32415115, 2020). "We conclude that MEGF11 plays an important role in tumour survival and that overexpression of MEGF11 induces both a cytokine and a chemokine cascade, which will favour the tumour microenvironment in terms of distant metastasis." (PMID 32415115, 2020). "Patients with tumours that over-expressed MEGF11 had a poorer prognosis." (PMID 32415115, 2020). "Furthermore, no circulating mouse 4T1 cells were selected by 6-thioguanine in the ∆MEGF11 4T1 line, which suggests that MEGF11 also plays an important role in tumour metastasis." (PMID 32415115, 2020). "After MEGF11 was knocked down in 4T1 cells (ΔMEGF11 4T1), there was a decrease in implanted tumour weight and AKT-mTOR signalling compared to the wild type MEGF11." (PMID 32415115, 2020).
MEGF11 also shares sentences with these, for which no sentence is quoted: developmental delay (1 paper); retinal disorder (1).